BLOC1S6 (biogenesis of lysosomal organelles complex 1 subunit 6)
Description:
Component of the BLOC-1 complex, a complex that is required for normal biogenesis of lysosome-related organelles (LRO), such as platelet dense granules and melanosomes. In concert with the AP-3 complex, the BLOC-1 complex is required to target membrane protein cargos into vesicles assembled at cell bodies for delivery into neurites and nerve terminals. The BLOC-1 complex, in association with SNARE proteins, is also proposed to be involved in neurite extension. May play a role in intracellular vesicle trafficking, particularly in the vesicle-docking and fusion process.
Synonyms: PA; PLDN; HPS9; BLOS6; PALLID
Tractability: Antibody: UniProt places it where antibodies can reach, with high confidence. PROTAC: ubiquitination databases record sites on it.
Gene: Protein-coding gene on chromosome 15 (45,587,214 to 45,615,945, forward strand). Ensembl gene ENSG00000104164.
Subcellular location: Cytoplasm; Membrane
Pathways (Reactome):
Vesicle-mediated transport: Golgi Associated Vesicle Biogenesis
Gene Ontology:
Molecular function: actin filament binding; identical protein binding; protein binding; protein homodimerization activity; syntaxin binding; AP-3 adaptor complex binding; molecular adaptor activity
Biological process: endosome to melanosome transport; melanosome transport; positive regulation of pigment cell differentiation; anterograde axonal transport; anterograde synaptic vesicle transport; melanosome organization; neuron projection development; actin filament network formation; adenosine metabolic process; amino acid metabolic process; angiogenesis; aspartate metabolic process; axo-dendritic protein transport; cellular response to epidermal growth factor stimulus; circadian sleep/wake cycle; cytoskeleton organization; dendrite morphogenesis; dentate gyrus development; developmental pigmentation; endosomal transport; endosome organization; eye pigmentation; gene expression; glutamate metabolic process; glutamine metabolic process; and 26 more
Cellular component: BLOC-1 complex; cytoplasm; membrane; transport vesicle; cytosol; actin filament; axon cytoplasm; axon terminus; cell body; cell-cell contact zone; ciliary basal body; contractile ring; cytoplasmic vesicle; dendritic spine; endoplasmic reticulum lumen; endosome; filamentous actin; focal adhesion; microvesicle; multivesicular body, internal vesicle; ruffle; stress fiber; synaptic vesicle
Genetic constraint (gnomAD): Loss-of-function variants: 18 observed, 17.76 expected, observed/expected ratio (o/e) 1.01, 90% interval 0.7 to 1.5. The upper end of that interval is the gene's LOEUF score, 1.5, which puts it in group 6 of 6, group 1 being the genes least tolerant of losing a copy. Missense variants: 143 observed, 153.99 expected, observed/expected ratio (o/e) 0.93, 90% interval 0.81 to 1.07. Synonymous variants: 64 observed, 55.86 expected, observed/expected ratio (o/e) 1.15, 90% interval 0.94 to 1.41.
Gene-disease validity (ClinGen):
ClinGen rates the evidence that BLOC1S6 causes each of these diseases.
Hermansky-Pudlak syndrome 9 (autosomal recessive): Definitive.
Homologues: Orthologues: rabbit BLOC1S6 (91% identical), pig BLOC1S6 (89% identical), mouse Bloc1s6 (87% identical), chimpanzee BLOC1S6 (86% identical), rat Bloc1s6 (86% identical), macaque BLOC1S6 (85% identical), guinea pig BLOC1S6 (79% identical), tropical clawed frog bloc1s6 (70% identical), zebrafish bloc1s6 (55% identical), Drosophila melanogaster Pldn (23% identical).
Diseases named in the same sentence as BLOC1S6 in open-access papers:
BLOC1S6 is named in the same sentence as 11 diseases in open-access papers, as found by Europe PMC text mining. Sharing a sentence is not in itself a finding about the gene and the disease. The quoted sentences say what the papers report.
lung carcinoma (1 paper, 2022). "BLOC1S6 is a gene with its functions basically unknown but its expression levels found to be inversely proportional in lung cancer patients’ survival." (PMID 35847855, 2022).
BLOC1S6 also shares sentences with these, for which no sentence is quoted: albinism (3 papers); Hermansky-Pudlak syndrome (2); Hermansky-Pudlak syndrome type 9 (2); Immunodeficiency (2); Chediak-Higashi syndrome (1); congenital neutropenia (1); Griscelli syndrome (1); Menkes syndrome (1); oculocutaneous albinism type 1 (1); ovarian carcinoma (1).